NFATC1 (nuclear factor of activated T cells 1)
Diseases named in the same sentence as NFATC1 in open-access papers (continued):
Sharing a sentence is not in itself a finding about the gene and the disease.
cancer (continued). "Thus, our study is the first to our knowledge to reveal the novel molecular mechanism of NFATc1 inhibition by mTORC1-mediated phosphorylation, which will exert broad impact on multiple fields including bone, immunology, and cancer." (PMID 30271915, 2018). "The distinct roles of NFATc1 in diverse cancer types might be explained by differential expression of NFATC1 isoforms in these tumors." (PMID 30085405, 2018). "Importantly, our mechanistic investigation identifies a previously unrecognized but fundamentally important calcineurin ⊣ mTORC1 ⊣ NFATc1 phosphorylation-regulatory signaling cascade that will broadly impact many fields such as bone, immunity, and cancer." (PMID 30271915, 2018). "The authors proposed since chronic inflammation is a known etiology of pancreatic AD, NFATc1 might be a crucial factor involved in the progression of this cancer." (PMID 28737489, 2017). "Recent discoveries, such as NFATc1 pro-angiogenic effect in retinal microvascular endothelial cells, the association of NFATc3 and NFATc4 with immune-related diseases, and the significant contributions of NFAT proteins to cancer progression, highlight the importance of these molecules and pathways." (PMID 39822413, 2024). "In addition, constitutively active NFATc1 disrupts the mechanisms that regulate physiological cell proliferation and differentiation in 3T3-L1 cells, transforming these immortalized cells and turning them into cancer cells." (PMID 36434268, 2022). "Therefore, inhibition of the interplay between PIM kinases and NFATC1 may have therapeutic implications for patients with metastatic forms of cancer." (PMID 31730483, 2019). "Interestingly, Nfatc1 gene is found to be overexpressed in many cancers, and its loss is linked with constant hair cycling and no quiescence." (PMID 23738074, 2013). "Further investigations revealed that NFATc1 simultaneously regulates both NADK and MDM2, which collectively promote metabolic reprogramming and cell cycle progression, thereby accelerating cancer cell proliferation." (PMID 41203626, 2025). "Super-enhancers have been found in genes involved in T-cell activation (IL2RA/CD25, CD30, and FYN) and known cancer genes (TP73, CCR4, TIAM2, NFATC1, NFATC2, and PIK3R1) in ATL cells." (PMID 38791169, 2024). "Previous studies have shown that the AKT/GSK3β/c-Fos/NFATc1, IGF-1/AKT/NF-κB (RelA) or TGF-β/Smad3/4 signaling cascade play a key regulatory role in BMM of many cancers." (PMID 37337244, 2023). "We found that the significantly activated regulons were involved in T cell biology (RORC, TCF7, NFATC1, and LEF1) or disease pathogenesis (IKZF2 for CD30+ TMF and BATF3 for cALCL) or reported cancer biology (POUZAF1 and TSHZ2)." (PMID 37790936, 2023). "NFATC1 is a member of the nuclear factor of activated T cell (NFAT) family and is upregulated in various cancers and mediates cell growth, migration, and invasion." (PMID 35327110, 2022). "The ability of cancer cells to migrate and invade was significantly inhibited after AHNAK or NFATC1 was knocked down." (PMID 35958586, 2022). "The future elucidation of the HSC70/HSP60-KBTBD11 interaction-related NFATc1 protein regulation could pave the way to potential proliferation- and differentiation-related applications not only in adipocytes but also in various other cell types, including osteoclasts and cancer cells." (PMID 36434268, 2022). "TFs associated with PIK3CA mutations were involved in WNT signaling, epithelial–mesenchymal transition, and cancer stem cell transition, including ELF3, TFEC, STAT4, STAT5B, NFATC1, GLIS1, CDC5L and AR." (PMID 36243974, 2022). "The mRNA expression of NFATc1 was also explored in the six PDAC cell lines PANC-1, BxPC-3, MiaPaCa-2, AsPC1, Capan-1 and SUIT-2 in comparison to the non-cancer immortalized human pancreatic duct epithelial cell line HPDE-E6E7." (PMID 34572796, 2021).
cancer (continued). "Survival analyses using the TCGA PAM50-based dataset for human basal-like cancers showed that patients with low EZH2, high NFATC1 or low (EZH2/NFATC1)-ratio have a worse prognosis compared to EZH2 high, NFATC1 low or high (EZH2/NFATC1)-ratio patients." (PMID 34845197, 2021). "NFATc1 acted via activation of COX-2 expression, which is an inducer of invasion and migration in many cancer cells." (PMID 34443374, 2021). "A77636 inhibited migration of cancer cells in a DRD1-dependent fashion and suppressed development of bone-resorbing osteoclasts by downregulating NFATc1 through the elevation of phosphorylation of eIF2α." (PMID 28374823, 2017). "Although the link between acidosis and RANK/NFATc1 mediated carcinogenesis or tumor promotion is not established, chronic activation of these factors through a dietary induced state of dysregulated acid-base status may contribute to cancer risk." (PMID 22853725, 2012). "It facilitates the expression of the cancer stem cell marker BMI1 (polycomb ring finger oncogene) by enhancing the influx of Ca2+ into the cytosol and promoting the nuclear translocation and activity of nuclear factor of activated T cell 1 (NFATC1)." (PMID 40661148, 2025). "Therefore, investigating the relationship between NFATc1 and MARCH8 in immune cells would be beneficial for advancing our understanding of cancer immunotherapy, immune dysfunction, autoimmune disorders, and infectious disease biology." (PMID 41023307, 2025). "Besides, the proliferation rate of cancer cells was significantly decreased after AHNAK and NFATC1 knockdown." (PMID 35958586, 2022). "In addition, the expression of programmed cell death protein 1 (PD-1), one of the most successfully targeted checkpoint proteins across various cancer types, including NSCLC, is induced by NFATc1 following T cell activation." (PMID 34917508, 2021). "Interestingly, NFATc1- and EZH2 co-occupied genes were involved in pathways with critical implications in cancer, such as calcium or Hippo signaling." (PMID 34943970, 2021). "Copy number losses of CRK (P = 0.07), SMAD2 (P = 0.09), FHIT (P = 0.68), and NFATC1 (P = 0.11) genes did not vary significantly between diffuse-type cancers and intestinal-type cancers." (PMID 26360582, 2015). "In non-metastatic cancer cells, NFATc1 drives Orai3 transcription, increasing its levels." (PMID 41023307, 2025). "Our findings will pave the road for future investigations to examine whether this NFATc1→Nur77→Cblb—•NFATc1 negative feedback loop may be widely applicable to NFATc1 regulation of other cellular processes such as T cell activation and cancer development." (PMID 26173181, 2015). "In univariate analysis, we found 17 significant genes, located on 3p14.1, 3q13.2, 17q12, and 18q22.1; these genes included cancer-related genes, such as FOXP1, GRB7, and NFATC1, indicating that altered expression of specific genes through CNAs could influence the clinical course of patients." (PMID 26465158, 2015). "Our data suggest that targeting the NFATc1 signaling in EZH2low TNBC/BLBC patients could represent an attractive opportunity to increase the efficiency of conventional chemotherapeutic treatments and reduce the development of deadly resistant cancer cells phenotypes." (PMID 34845197, 2021).
infection (30 papers, 2009 to 2026). The state of being infected such as from the introduction of a foreign agent such as serum, vaccine, antigenic substance or organism. "Western blot analysis also showed a significant enhancement in expression of NFATc1 during the late phase of infection with a maximum increase at 48 h postinfection (3.1-fold over uninfected cells, p < 0.0001, F = 26.96)." (PMID 38750790, 2024). "We investigated the role of NFAT signaling in acute infection of BMC animals, and observed that antigen-specific responses from NFATc1-deficient or NFAT DKO CD8+ T cells were impaired in lungs, but not in lymph nodes or spleen." (PMID 38346075, 2024). "Nuclear translocation kinetics of NFATc1 in infection was also found to be in synchronization with its expression (2.5-fold over uninfected control, p < 0.0001, F = 14.69)." (PMID 38750790, 2024). "We show that NFAT-deficient CD8+ T cells can mount robust CMV-specific responses following acute infection, but NFATc1 is indispensable for maintaining persistent CD8+ cell responses during the chronic phase." (PMID 38346075, 2024). "The expression of C6, C7, IRAK4, LBP, and RIPK2 was significantly upregulated after infection with A. hydrophila, while the expression of SIPA1L2 and NFATC1 was significantly downregulated after infection." (PMID 36910190, 2023). "The percentages of splenic NFATc1+ CD4 T cells were remarkably increased with prolonged infection and picked on day 16 (about 60%)." (PMID 36091043, 2022). "Nuclear factor of activated T cells 1 (NFATc1) was found to be a key transcription factor to induce PD-1 expression after infection." (PMID 36091043, 2022). "Overall, scRNA-seq data confirm that T2 LCLs are much more likely to enter fully lytic infection than T1 LCLs, and suggest that both viral and cellular factors (including NFATc1, IRF4 and EBF1 levels) contribute to this difference." (PMID 35472072, 2022). "Instead, our results point to differences in the expression and activation of NFATc1 and NFATc2 as a primary mechanism driving enhanced lytic infection in T2 EBV-infected B cells." (PMID 32059024, 2020). "Subsequently to canonical pathway activation, Wnt/Ca+2 pathway was activated; since we have demonstrated an Wnt proteins-dependent upregulated of p-CaMKII-Thr286 and activated NFATc1 expression after infection." (PMID 29743880, 2018). "Following infection with shRNAs, we confirmed target gene knockdown by qRT-PCR and examined changes in the expression of c-Fos, Nfatc1, Dc-stamp and Ctsk genes important for osteoclast formation or function." (PMID 28953929, 2017). "Correspondingly, no detectable PD-1 level was obtained in the cyclosporine A-treated infected cells further suggesting the importance of NFATc1 in regulation of PD-1 in infection." (PMID 28690843, 2017). "At 12 h after infection, NFATc1 was detected in nuclear lysates when osteoclasts were infected with live or UV-inactivated DV, suggesting that NFATc1 translocation is independent of DV replication." (PMID 27033255, 2016). "Infection of osteoclast precursor cells with P. gingivalis markedly stimulates osteoclastogenesis in an NFATc1 dependent but NF-κB independent manner." (PMID 22723864, 2012). "In wild-type and Myd88−/−Trif−/− BMMφ, T. cruzi trypomastigotes infection induced nuclear translocation of NFATc1." (PMID 19609356, 2009). "In OCI-Ly3 (ABC-origin DLBCL) cells, nuclear translocation of CagA, nuclear p-CagA expression, and nuclear localization of NFATc1 were simultaneously observed 1 and 6 h after HP (HM#2) infection, whereas cytoplasmic p-NFATc1 expression decreased at 1 and 6 h after HP (HM#2) infection." (PMID 39558403, 2024). "However, this is contrary to previous findings for DENV, where infection-mediated NFATC1 translocation is reported in DENV-infected OCs." (PMID 35670284, 2022).
infection (continued). "Together, these data suggest that expression of NFATc1 is important in osteoclastogenesis in RANKL-primed RAW-D cells induced by infection with P. gingivalis, and the down-regulation of IFNβ expression induced by P. gingivalis may facilitate induction of osteoclast differentiation." (PMID 22723864, 2012). "In response to an infection, transcription factors such as fork-head box protein O1 (FOXO1) and nuclear factor of activated T cells, cytoplasmic 1 (NFATC1) upregulate the expression of PD-1 on antigen-activated T cells as they eliminate the pathogen." (PMID 39339217, 2024). "We show selective impacts of NFATc1 and/or NFATc2 genetic ablations on the long-term inflation of MCMV-specific CD8+ T cell responses despite largely maintained responses to acute infection." (PMID 38346075, 2024). "Instead, we find that T2 LCLs express much higher levels of activated NFATc1 and NFATc2, and that cyclosporine (an NFAT inhibitor) and knockdown of NFATc2 attenuate constitutive lytic infection in T2 LCLs." (PMID 32059024, 2020). "The infection rates of the retroviral GFP control and the retroviral constitutively active (CA) NFATc1-GFP were similar in either BMMs treated or untreated with the fermented antler extract." (PMID 23509596, 2013). "Inhibitors of NFATc1 (FK506) and p38 MAPK (SB203580), similarly inhibited osteoclastogenesis in RANKL-primed RAW-D cells induced by infection with P. gingivalis." (PMID 22723864, 2012). "To elucidate the mechanism of osteoclast induction, we analyzed the effect of inhibitors of NFATc1, MAPK, and NF-κB pathways on osteoclastogenesis in RANKL-primed RAW-D cells induced by infection with P. gingivalis." (PMID 22723864, 2012). "While STAT3's role in Theileria infections is well-established, the functions of the others (GTF2F1 and NFATC1) remain unclear." (PMID 40368139, 2025). "Notably, 12 of these TFs exhibited distinct phosphorylation patterns upon infection, including MED14, SIN3A, BCL6, cJUN, NFATC1, STAT3, RUNX3, GTF2F1, MED1, JUNB, TLE3, and FOSL2." (PMID 40368139, 2025). "Administration of inhibitors of NFATc1 and HIF-1α in infected mice depicted similar observations and justifies the role of these two transcription factors in IL-33 secretion and propagation of infection." (PMID 38750790, 2024). "In vitro and in vivo experiments further identified the transcription factors nuclear factor of activated T cell 1 (NFATc1) and hypoxia-inducible factor 1 alpha (HIF-1α), which are activated by calcium-dependent phosphatase calcineurin and lead to IL-33 production during infection." (PMID 38750790, 2024). "TH1- and TH2-related transcripts included Nfatc1, Cd4, Runx3, and Gata3, suggesting that TH1 cells may be a significant contributor to interferon-gamma (IFNγ) production during infection in the adipose tissue." (PMID 37923768, 2023). "Thus, we propose that increased IRF4 expression in T1 LCLs reduces lytic infection not only by attenuating BCR signaling, including NFAT activation, but also by decreasing NFATc1 and NFATc2 expression." (PMID 35472072, 2022). "Although inhibitors of both of NFATc1 and NF-κB inhibited osteoclastogenesis induced by RANKL, a specific inhibitor of NFATc1, but not an inhibitor of NF-κB, inhibited osteoclastogenesis induced by infection with P. gingivalis in RANKL-primed RAW-D cells." (PMID 22723864, 2012). "Notably, the gene expression profile associated with cell cycling was uniquely altered in the absence of NFATc1, and this transcriptional shift was evident even during the acute infection phase." (PMID 38346075, 2024). "However, the fraction of NFATc1 and NFAT DKO CD8+ T cell populations was significantly reduced during latency for both epitopes tested, where the contraction occurred by 14 days post infection and the populations were stably reduced thereafter." (PMID 38346075, 2024). "We found that NFATc1 located in the cytosol (green color) without DV infection (mock control)." (PMID 27033255, 2016).
infection (continued). "Immunofluorescence data (26 h after initiating coculture with or without the HP strain) showed that NFATc1 was localized in the nucleus of MA-1#46, OCI-Ly3, and OCI-Ly7 cells after infection with HP (HM#2)." (PMID 39558403, 2024). "In contrast, infection (i.e., retreatment) of RANKL-primed cells with live P. gingivalis increased expression of NFATc1 but not of c-fos." (PMID 22723864, 2012). "However, unlike NFATc1, cytosolic HIF-1α was also decreased in case of pretreatment of cyclosporin A, thus indicating a role of calcineurin in the stabilization of HIF-1α following infection." (PMID 38750790, 2024).
cardiovascular disease (5 papers, 2015 to 2023). "We constructed an mRNA–miRNA–lincRNA ceRNA interaction network centered on miR-22-3p and used the starBase v2.0 and miRWalk databases to predict eight related transcription factors associated with cardiovascular disease, namely, CTCF, JUN, JUND, NFATC1, NFE2L2, RAD21, RELA, and TAL1." (PMID 36105099, 2022). "NFAT protein family is the main substrate of CaN and includes NFAT1 (NFATc2), NFAT2 (NFATc1), NFAT3 (NFATc4), NFAT4 (NFATc3) and NFAT5, among which NFATc3 protein is highly related to the development of cardiovascular disease." (PMID 37735624, 2023). "The influence of CD137 signaling on the expression of NFATc1 through TRAF6 and NF-κB p65 may have extensive implications for the diagnosis and therapeutic intervention for a variety of proliferative cardiovascular diseases." (PMID 26600673, 2015).
bone disorder (4 papers, 2021 to 2025). "Therefore, a greater knowledge of NFATc1 regulation in osteoclasts will be critical for the understanding of bone disorders and the development of novel anti-resorptive therapeutics." (PMID 37020186, 2023).
inflammation (3 papers, 2014 to 2022). Aberrant reaction of the microcirculation characterized by movement of fluid and leukocytes from the blood into extravascular tissues. "NFATc1 is an important member of the nuclear factor family of activated T cells and primarily affects lymphocyte proliferation and TH2-type immune responses in airway inflammation." (PMID 35037821, 2022).
immune diseases (2 papers, 2020 to 2025). "Nuclear factor of activated T-cells 1 (NFATc1) is used to develop immune modulatory drugs, such as tacrolimus and cyclosporine A, for controlling immune diseases." (PMID 32111037, 2020).
kidney (2 papers, 2018 to 2023). "In conclusion, measuring NFATc1 amplification is a direct method to determine the biological effects of TAC on divers T cell subsets in whole blood samples of kidney transplant recipients." (PMID 30036394, 2018). "In conclusion, our results verify the reno-protective potential of AEA against HgCl2-induced kidney injury by its anti-inflammatory, antioxidant, and anti-apoptotic capacities by modulating WNT-5A/BCL-2, IP3/NFATC1, HMGB-1/RAGE/NF-κB, caspase-1/IL-18, and caspase-3/BCL-2 cues." (PMID 37488162, 2023).
kidney diseases (2 papers, 2023). "In this work, we discovered 20 top eccDNA hub genes in which NCAM1, NFATC1, PRKCB, LEF1, PRKAG2, and GRM8 were strongly linked to a variety of kidney disorders." (PMID 36967395, 2023).
adenocarcinoma (1 paper, 2018). A common cancer characterized by the presence of malignant glandular cells. "Targeted expression of the activated nuclear form of NFATc1 in a mouse model leads to PIN and subsequently adenocarcinoma marked by an elevated expression of proinflammatory cytokines, apparent proliferative influence of NFATc1+ cells on the neighboring cells, and castration resistance." (PMID 29671777, 2018).
NFATC1 also shares sentences with these, for which no sentence is quoted: renal fibrosis (4 papers); COVID-19 (3); Down syndrome (3); hematological malignancies (3); liver cancer (3); acute kidney injury (2); bacterial infection (2); cervical cancer (2); chronic apical periodontitis (2); Heart Disease (2); Kawasaki disease (2); leprosy (2); multiple myeloma (2); non-small cell lung carcinoma (2); oral lichen planus (2); Osteopenia (2); Richter syndrome (2); Splenomegaly (2); vasculitis (2); abdominal aortic aneurysm (1); acne vulgaris (1); adenopathy (1); alcohol (1); autism spectrum disorder (1); Autoimmune Addison’s Disease (1); Bicuspid aortic valve (1); cardiac conduction disease (1); chronic myeloid leukaemia (1); chronic obstructive pulmonary disease (1); chronic periodontitis (1).
A further 46 diseases each share a sentence with NFATC1 in 1 paper.